APP (amyloid beta precursor protein)
Diseases named in the same sentence as APP in open-access papers (continued):
Sharing a sentence is not in itself a finding about the gene and the disease.
breast cancer (continued). "However, advanced breast cancers may struggle to survive in the absence of APP, presumably because they have evolved to survive better, at least in part, in an APP-dependent manner." (PMID 25491510, 2014). "Recently, a study done on non-luminal breast cancers (Her2+ and TNBC), published in EBioMedicine, identified soluble APPα that is generated by ADAM10 cleavage of APP, as important in breast cancer tumor migration and proliferation." (PMID 32265938, 2020).
depression (53 papers, 2011 to 2026). "APP is also linked to inflammation, synaptic dysfunction, and neurogenesis, all of which have also been proposed to contribute to the pathogenesis of depression." (PMID 41451799, 2025). "Importantly, Trp treatment ameliorated MGO-induced depression like-behavior and memory loss in mice and markedly mitigated increased expression of p-Tau, APP, p-ERK1/2, p-pJNK, and p-NF-κB in the brain." (PMID 39574138, 2024). "Thus, early olfactory deficits could lead to the identification of depression patients with high risk of developing AD, as also occurs in our APP/PSEN1-Tg animals by showing early depression-like behaviour with later hyposmia traits." (PMID 33795014, 2021). "In recent work, multiple AD-related models were congruent with a human depression portrait, including APPsa knock-in, APP knockout, APP/PS1 mutation, and APLP2 knockout and this is consistent with the finding of overlaps between AD and depression portraits." (PMID 38236817, 2024). "Based on this, we focused on exploring the potential involvement of miR-451a in the co-pathogenesis of AD and depression using APP/PS1 double transgenic mouse model for AD." (PMID 37284450, 2023). "Decreased PGD2 in depression is associated with depressive behaviour 27, but other studies have indicated that PGD2 promotes apoptosis in APP/PS1 mice." (PMID 34671214, 2021). "Taking another pharmaceutical molecule as an example, the common anti-depression medicine fluoxetine strongly suppressed astrocyte activation in an APP/PS1 mouse model." (PMID 31439031, 2019). "Different studies have in fact sought to discriminate between subjects undergoing normal aging from those suffering from depression or AD through the measurement of the various APP cleavage products." (PMID 27034847, 2016). "Progressive behavioral changes have previously been described in the APP/PS1 transgenic mouse model but there has yet to be a study focusing on depression-related behaviors." (PMID 25806005, 2015). "In the current study, we found that overexpression of miR-451a in the mPFC could improve long-term memory, social ability, and depression-like behavior in APP/PS1 mice." (PMID 37284450, 2023). "We further investigated whether overexpression of miR-451a in the mPFC rescued cognitive defects and depression-like symptoms of APP/PS1 mice." (PMID 37284450, 2023). "Taken together these findings suggest that influence of lithium on APP may be a common mode of action of lithium effect on both AD and major depressive disorder." (PMID 30618562, 2018). "Furthermore, differences between MDD and BPD were seen for matrix-associated growth factors APP and SPARC, immune gene TNF, and transcription factors CREB1, NFKB1, and NR3C1 when controlling for depression severity, age, and medication use." (PMID 24143878, 2013). "In major depression, APP interacted with the abnormally expressed NF1." (PMID 22373040, 2011). "While much remains to be discovered about the potentially important role of depression in AD pathology, it is interesting to note that antidepressant drugs, whose actions often involve reductions in GC secretion, inhibit the proteolytic cleavage of APP into amyloidogenic products." (PMID 27034847, 2016). "Notable nodes that appeared over at least two models included C9orf72, TREM2, APP and MAPT with relationships to input nodes of musculoskeletal and joint disorders, deafness and depression." (PMID 38383858, 2024). "The link between AD-related mouse lines and depression was high with multiple AD models (e.g., humanized APP/PS1, APP KO, APLP2 KO) being among the top 20 matches and this finding is consistent with studies identifying high comorbidity of AD and depression." (PMID 34997033, 2022).
depression (continued). "While specific confirmation in APP/PS1 or 5xFAD models is pending, mechanistic extrapolations from major depressive disorder (MDD) and stress-related neuroinflammation studies strongly support a role for microbiota-derived miRNAs and EVs in the modulation of CNS targets by the vagus." (PMID 41299728, 2025). "Our data revealed that MGO-induced depression like-behavior and memory deficits resulted from disturbances in Trp, 5-HT, BDNF, and NGF levels, increased p-Tau and APP expression, neuroinflammation, and impaired redox status (Nrf-2/Ho-1/TXNRD1/Sirt3/5) in the brain." (PMID 39574138, 2024). "In our regression analysis of depressed patients only, we did find that medication use led to differences in expression when controlling for age, depression severity, and diagnosis, including increased expression of ASIC receptors, transcription factor NR3C2, and growth factor APP." (PMID 24143878, 2013). "Of the growth factors that we examined, we observed that female patients with depression displayed elevated levels of amyloid precursor protein (APP) mRNA compared to healthy non-depressed controls." (PMID 24143878, 2013). "We found that APBA1/2 related with amyloid beta A4 precursor protein (APP) metabolism in AD was correlated with 5-HT6R in depression patients, and regulated by 5-HT6R in the AD mouse model, suggesting significant implications for the network of 5-HT6R between AD and depression." (PMID 26449188, 2015).
Insulin resistance (53 papers, 2012 to 2025). Increased resistance towards insulin, that is, diminished effectiveness of insulin in reducing blood glucose levels. "In this study, we examined the effects of streptozotocin-induced insulin deficiency or a high-fat, high-sugar (HFHS) diet-induced insulin resistance on cognitive function in knock-in AD mouse models expressing human mutant APP and wild-type tau." (PMID 40964391, 2025). "Insulin resistance reduces the supply of glucose, which is the main energy source of the brain, affects the metabolism of APP, and causes hyperphosphorylation of tau protein, which can lead to AD." (PMID 36834911, 2023). "The levels of NEFA, a risk factor for the development of insulin resistance, in the APP and KBP groups were lower than those in the control group." (PMID 36360046, 2022). "Underlying mechanisms of insulin resistance leading to cognitive dysfunction are an increased tau protein concentration, altered hippocampal plasticity, altered amyloid precursor protein (APP) metabolism, and altered inflammatory response in the brain." (PMID 35661882, 2022). "Interestingly, under obesogenic conditions there was a complete reversal of each of these mutant APP-associated effects, and a concomitant exacerbation of obesity-induced insulin resistance, triglyceride elevation, and macrophage infiltration." (PMID 22912823, 2012). "In addition, excessive temporal glucose elevation, probably due to delayed glucose uptake caused by insulin resistance, was observed in APP/IR‐dKI mice compared with APP‐KI mice, which indicates glucose fluctuation in the APP/IR‐dKI mice through daily maintenance by feeding normal rodent chow." (PMID 37822109, 2023). "APP/IR‐dKI mice exhibited insulin resistance and an earlier onset of cognitive dysfunction than APP‐KI mice." (PMID 40443027, 2025). "Through the analyses of APP/IR‐dKI mice, we have clarified the relationship between insulin resistance and BPSD." (PMID 40443027, 2025). "Of note, activated AKT and ERK were also suggested to be the major kinase for tau phosphorylation and APP deposition in AD, and the brain insulin resistance emerging in AD further induces the decreased phosphorylation levels of AKT and ERK." (PMID 39626951, 2024). "Brain insulin resistance triggers the accumulation of APP toxic fragments (e.g., Aβ and -C99) either by favoring an aberrant APP cleavage or by inhibiting their clearance." (PMID 36670973, 2023). "We crossbred the IR‐KI and APP‐KI mice and analyzed the resultant mice (APP/IR‐dKI mice) to investigate the pathological role of insulin resistance in AD exacerbation." (PMID 37822109, 2023). "In our study, APP/IR‐dKI mice exhibit insulin resistance not only in the brain but also in the whole body." (PMID 37822109, 2023). "Our study confirmed that HFD induces an increase in body weight, hyperglycemia and insulin resistance in APP/PS1 mice accompanied by the downregulation of IRS2 protein levels in the liver, a protein involved in insulin signaling regulation." (PMID 36895036, 2023). "Nevertheless, insulin resistance abolished the effect of IGF-I on APP phosphorylation at T688, suggesting that treatment with insulin and IGF-I cannot be beneficial in AD patients with insulin resistance, metabolic syndrome, or diabetes." (PMID 38203429, 2023). "In the present study, to clarify the effects of insulin resistance on the preclinical pathology of AD, we compared APP‐KI mice with APP/IR‐dKI mice by focusing on cholinergic function." (PMID 37822109, 2023). "During the development of brain insulin resistance, ceramide promote cleavage of amyloid beta precursor protein (APP) by β and γ-secretase to produce Aβ, which is the pathogenic molecule of AD." (PMID 35661963, 2022). "WD-induced insulin resistance affects processes involved in amyloidogenic APP proteolysis and Aβ peptide formation in the entorhinal cortex." (PMID 35563135, 2022).
Insulin resistance (continued). "We also reported that silencing of Sirt3 gene in APP/PS1 mice results in exacerbation of insulin resistance, neuroinflammation and β amyloid plaque deposition." (PMID 36396721, 2022). "To induce insulin resistance-like phenotype, we fed APP/PS1 and C57 WT mice with HFD for 6.5 months and, as expected, HFD treatment resulted in weight gain, liver histopathological changes and insulin resistance for both types of mice." (PMID 33291072, 2020). "Remarkably, the central infusion of AβOs lead to peripheral insulin resistance, which was further observed in the APP/PS1 and in the 3xTgAD mouse models of AD." (PMID 32365816, 2020). "Collectively, these data indicate a potential contribution of genetic and diet-induced insulin resistance in preceding AD pathology in aging APP/PS1 mice." (PMID 33291072, 2020). "Hypoglycemia, possibly as a result of brain insulin resistance leads to decreased O-GlcNAcylation of APP and Tau resulting in their hyperphosphorylation and production on toxic Aβ amyloid and Tau aggregates which are hallmark features of AD." (PMID 31143098, 2019). "The total levels of IRβ and AKT were significantly decreased in APP/PS1 mice, and the levels of IRS1 pS636 and IRS1 pS612, which play a central role in insulin resistance, were significantly increased in APP/PS1 mice compared with wild‐type controls." (PMID 27457264, 2016). "Constitutive knock‐in mice with the P1195L mutation in the insulin receptor (IR‐KI mice) and those with a mutated amyloid precursor protein (AppNL‐G‐F mice: APP‐KI mice) were crossbred to obtain the resultant mice (APP/IR‐dKI mice) as AD models with insulin resistance for behavioral analysis." (PMID 40443027, 2025). "Moreover, insulin resistance exacerbates the pathological features of AD by influencing the processing of amyloid precursor protein (APP) and tau phosphorylation." (PMID 40724831, 2025). "It has been found that insulin resistance increased APP metabolism and BACE-1 expression." (PMID 40076550, 2025). "Insulin resistance and impaired glucose metabolism in the brain may alter glycosylation of APP, an important post-translational modification in the APP processing pathway, and favor Aβ formation." (PMID 35784855, 2022). "There is also evidence that brain insulin resistance may upregulate APP and b-secretase 1 (BACE 1) and increase, by extension, Ab formation." (PMID 35453527, 2022). "In addition, the pancreas expresses amyloid precursor protein (APP), and there is a suspicion of a contribution of Aβ-induced damage in the pancreas to insulin resistance-linked alterations in AD." (PMID 34065168, 2021). "Neuronal insulin resistance instigated by hyperphosphorylation of IRS-1 at the Ser636/312/307 residues and downregulation of p-IRS-1Tyr 632 has been associated with AD pathology and reported in Aβ and APP/PS1 mouse AD models as well as HFD and Adipo−/− mice." (PMID 33849621, 2021). "Our present study evaluates the effect of a chronic administration of DXI in the inflammatory process surrounded AD development, but also in the metabolic alterations such as weight gain, hyperglycemia and insulin resistance induced by HFD intake in APP/PS1 mice." (PMID 34294142, 2021). "Moreover, Jiménez-Palomares’s study further indicated that increased Aβ production prompts the onset of glucose intolerance and insulin resistance in db/+;APP/PS1 model mice." (PMID 33291072, 2020). "Another study showed that insulin resistance can alter APP processing by activating autophagy." (PMID 32326589, 2020). "Neuronal insulin resistance impairs neuronal glucose uptake and metabolism, which results in both direct neuronal dysfunction and increased generation of amyloid through upregulation of the amyloid precursor protein (APP)." (PMID 29706884, 2018). "Elevated APP also activates the Jnk domain impairing mitochondrial metabolism and increasing oxidative stress rates, which promote additional system wide but particularly brain insulin resistance." (PMID 29326659, 2017).
Insulin resistance (continued). "Additionally, mutant APP was observed to significantly exacerbate insulin resistance, triglyceride elevations, and macrophage infiltration of adipose tissue in response to a high fat diet." (PMID 22912823, 2012). "Cerebral insulin resistance results in disinhibition of glycogen synthase kinase-3β (GSK-3β) that promotes tau hyperphosphorylation and amyloidogenic processing of the amyloid precursor protein (APP); thus, disrupted insulin signaling is linked to the classical AD pathologies." (PMID 41226821, 2025). "In a glucose tolerance test performed at 11 months of age, APP/PS1/Hif-p4h-2gt/gt mice showed improved glucose clearance from blood compared with APP/PS1/Hif-p4h-2wt/wt, and they had lower fasting insulin levels and insulin resistance scores." (PMID 40609789, 2025). "There was not significant difference in FBG, plasma insulin and homeostasis model assessment of insulin resistance (HOMA-IR) levels between C57 and APP/PS1 control mice." (PMID 40341393, 2025). "The APP/PSEN1 mice appeared resistant to the hypoxia-mediated trend for lower insulin levels and lesser insulin resistance seen in wt." (PMID 35852609, 2022). "We observed significant exacerbation of peripheral and central insulin resistance and elevation of neuroinflammatory markers in APP/PS1/Sirt3-/- compared to APP/PS1 mice." (PMID 36396721, 2022). "Taken together, APP/IR‐dKI mice exhibited insulin resistance and larger glucose fluctuations than APP‐KI mice did, without persistent hyperglycemia." (PMID 37822109, 2023). "APP/IR‐dKI mice, which exhibited insulin resistance without persistent hyperglycemia, showed early initiation of cognitive dysfunction and altered CBF regulation mediated by downregulation of the nicotinic acetylcholine α7 receptor (nAChRα7)." (PMID 37822109, 2023). "In this study, APP/IR‐dKI mice that showed insulin resistance without persistent hyperglycemia exhibited an earlier onset of cognitive dysfunction." (PMID 37822109, 2023). "In the present study, HFD-fed APP/PS1 mice exhibited increased escape latency and learning profile in Morris water maze (MWM) test in comparison with normal diet-treated control animals, which suggests diminished cerebellar function during insulin resistance." (PMID 33291072, 2020). "Our results demonstrated that APP/PS1-ob/ob mice showed severe diabetic symptoms including hyperglycemia and insulin resistance and may be used as an animal model for researching the relationship between T2DM and AD." (PMID 28467789, 2017). "Furthermore, APP+-ob/ob and APP/PS1-db/+ mice have shown increased glucose intolerance and insulin resistance compared with ob/ob mice." (PMID 26244977, 2015). "Second, when APP+-ob/ob mice were generated by crossing ob/ob (leptin homozygous mutants) mice with APP23 transgenic mice, further increases in hyperglycemia, hyperinsulinemia, and insulin resistance were observed." (PMID 26244977, 2015). "Here we established an AD model with whole‐body insulin resistance without persistent hyperglycemia (APP/IR‐dKI mice) by crossbreeding constitutive knock‐in mice with P1195L‐mutated insulin receptor (IR‐KI mice) and those with mutated amyloid precursor protein (AppNL‐G‐F mice: APP‐KI mice)." (PMID 37822109, 2023).